FGFR2 (fibroblast growth factor receptor 2)
Diseases named in the same sentence as FGFR2 in open-access papers (continued):
Sharing a sentence is not in itself a finding about the gene and the disease.
tumor (continued). "These alterations cause abnormal FGFR2 signaling, which in turn triggers downstream pathways like MAPK, PI3K/AKT, and STAT, leading to increased tumor proliferation and survival." (PMID 39195304, 2024). "We present a case of FGFR2 fusion to a novel 3′ partner at a common breakpoint near the FGFR2 C-terminus in a high-grade serous Mullerian primary adenocarcinoma, an unusual neoplasm type to harbor this fusion." (PMID 39759134, 2024). "Genomic alterations, such as FGFR2 amplification, lead to protein overexpression, enhancing oncogenic signaling and promoting tumor growth even with low ligand levels." (PMID 39195304, 2024). "In order to evaluate the occurrence of activated FGFR2 signalling in the tumor tissue of iCCA patients with FGFR2 GAs, we assessed the levels of protein phosphorylation of both FGFR2 and FRS2α, its main downstream target." (PMID 38326380, 2024). "Cellular experiments revealed that different FGFR2 genetic alterations promoted ICC tumor growth, invasion, and metastasis but responded differently to FGFR-selective small molecule kinase inhibitors (SMKIs)." (PMID 37964396, 2023). "Taken together, FGFR2-amplified primary adenocarcinoma of the GIT shows a high rate of heterogeneously distributed tumor clones." (PMID 36416959, 2023). "Future functional characterization is warranted to demonstrate the intercellular crosstalk between FAP(+) CAFs producing FGF20 and tumor epithelial cells having enhanced FGFR2 protein levels at the tumor invasive margin of EOCC." (PMID 37964075, 2023). "Collectively, these results show that the inactivation of ADAM17 results in the suppression of tumour growth, inhibition of cellular proliferation and increased apoptosis in FGFR2‐mutant ECs." (PMID 37165578, 2023). "Tumor epithelial cells at tumor invasive margin of EOCC tumors neighboring FAP(+) CAFs show significantly higher mRNA/protein levels of fibroblast growth factor receptor (FGFR2) and PI3K/Akt signaling activation." (PMID 37964075, 2023). "Across 396 analyzed patients, prevalence of potentially actionable alterations was comparable with the expected prevalence in advanced disease (13% FGFR2/3, 20% PIK3CA, 13% ERBB2, and 37% with elevated tumor mutational burden ≥10 mutations/megabase)." (PMID 37601688, 2023). "A subsequent validation in a separate cohort of a larger series of CC and HB non-tumor livers revealed elevated expressions of FGFR2, CEBPB in CC patients, though other DE genes didn’t show differential expressions." (PMID 36996081, 2023). "Potential ligand-receptor interaction analysis showed that FGF20 ligand produced in FAP(+) CAFs at EOCC tumor invasive margin had the highest interaction potential to bind to FGFR2 in PanCK(+) tumor epithelial cells at EOCC tumor invasive margin." (PMID 37964075, 2023). "In contrast, bile duct expression of CEBPB and FGFR2 were elevated in HB tumor regions as compared to the non-tumor regions." (PMID 36996081, 2023). "Given that activating FGFR2 mutations are exceptionally rare in ICC, future tumor-agnostic investigations focusing on FGFR site mutations harbor the potential to expand the applicability of FGFR inhibitors." (PMID 37964396, 2023). "We confirmed that both MET and FGFR2 were highly amplified in the primary tumor using FISH (MET–CEP7 ratio = 5 and FGFR2–CEP7 ratio = 3)." (PMID 38137393, 2023). "Positive PD-L1 expression by tumor cells was observed in only one of 58 FGFR2 fusion-positive ICC patients, but was detected in eight of the FGFR2 fusion-negative specimens." (PMID 36966334, 2023). "For example, the naturally active compound formononetin (25 μΜ) suppresses tumor growth and angiogenesis in MCF‐7 and MDA‐MB‐231 tumor models by targeting the FGFR2‐mediated Akt signaling pathway." (PMID 37132286, 2023). "Of note, we confirmed that both MET and FGFR2 were highly amplified in the primary tumor using FISH (MET–CEP7 ratio = 5 and FGFR2–CEP7 ratio = 3)." (PMID 38137393, 2023).
tumor (continued). "Preclinical data support the notion that co-inhibition of MET and FGFR2 enhances or restores the anti-tumor effect of FGFR2 inhibitors in co-amplified cancer cells." (PMID 38137393, 2023). "R203C and C382R mutations in FGFR2 were respectively harbored by two different patients, which have been reported in ICC and other tumor types likely oncogenic." (PMID 37964396, 2023). "FGFR2 expression was assessed in the primary tumor as well as in several lymph node metastases from the same patients by immunohistochemistry with three different antibodies (Abcam clone EPR24075-418, R&D clone 98706, Santa Cruz clone C-8)." (PMID 38155920, 2023). "FGFR2-positive diffuse type GCs classified as a small subset of patients with a poor tumor specific survival (5.29 ± 1.3 vs. 14.67 ± 1.9 months; p = 0.004)." (PMID 36260159, 2023). "While FGFR2 was detectable in tumor core and invasive areas, we observed expression of FGFR2 on GBM cells in the tumor core, but not invasion areas (arrows)." (PMID 37579831, 2023). "Next, we evaluated the correlation between FGFR2/MET amplification and tumor mutational burden (TMB) status (≥10 mutations/mb vs. <10 mutations/mb), microsatellite instability (MSI) status (MSS vs. MSI high), and PD-L1 CPS score (CPS 0 vs. ≥1)." (PMID 38137393, 2023). "Preclinical studies have demonstrated the anti-tumor efficacy of FGFR inhibition selectively in cells harboring FGFR2 gene fusions." (PMID 37954763, 2023). "CPL304110 inhibited tumor growth of the SNU-16 model with amplification of FGFR2 in the two highest treatment groups (40 and 60 mg/kg) in a dose-dependent manner." (PMID 38282676, 2023). "Sub-analyses of currently ongoing clinical trials investigating the efficacy of FGFR2 or pan-FGFR inhibitors in solid tumors will show the impact of heterogeneity of FGFR2-amplified tumor cell clones on treatment response or failure." (PMID 36416959, 2023). "Current studies identified abnormal FGFR2 signaling as an essential factor in carcinogenesis and a possible therapeutic approach for various tumor types." (PMID 38269250, 2023). "Among the FGFR family members (FGFR1, FGFR2, FGFR3, and FGFR4), only FGFR2 was significantly upregulated in PanCK(+) tumor epithelial cells at the EOCC tumor invasive margin compared to the LOCC tumor invasive margin in NGDSP analysis." (PMID 37964075, 2023). "For the medical-diagnostic routine, this means that in systemically ill patients who are to receive anti-FGFR2 therapy, FGFR2 biomarker testing should be extended to the biologically driving tumor component, which can also only become apparent in metastases." (PMID 36416959, 2023). "Initial screening of the primary patient tumours, PDXs and matched PDXOs for FGFR2 isoform status revealed similar patterns of FGFR2c splice isoform expression to that reported in a large clinical cohort of EC patients." (PMID 38062117, 2023). "Percentages of CEBPB-immuno-positive or FGFR2-immuno-positive bile duct cells in CC and HB-tumor liver were higher than that in HB non-tumor liver." (PMID 36996081, 2023). "Percentages of bile duct cells that were FGFR2+ve were significantly higher in HB tumor region than in CC and HB non-tumor livers." (PMID 36996081, 2023). "The highest frequency observed, 0.26%, was in biliary tract tumors, a tumor type known to be driven by FGFR2 alterations." (PMID 37980453, 2023). "We analyzed publicly available RNA-seq datasets of human and murine GBM and found in both a significant upregulation of FGFR2 RNA in tumor invasion zones." (PMID 37579831, 2023). "This suggests that sufficient sampling in the primary tumor and lymph node or organ metastases is advisable to determine the FGFR2 status." (PMID 36416959, 2023). "Of notice, FGFR2 was also detected as upregulated in FAP(+) stromal cells at the tumor invasive margin of EOCC." (PMID 37964075, 2023). "Taken together, oral administration of CPL304110 resulted in strong inhibition of growth of both patient-derived FGFR2-dependent tumor xenografts." (PMID 38282676, 2023).
tumor (continued). "The scale of this amplification event suggests a strong selective pressure for focal amplification of FGFR2 in EMT tumor 1356." (PMID 37805590, 2023). "In this study, we found that FGF20 was specifically detected in FAP(+) CAFs areas that were closely located to PanCK(+) tumor epithelial cells that had positive FGFR2 detection at EOCC tumor invasive margin." (PMID 37964075, 2023). "FGFR2 testing in metastases should be performed, because a small aggressive clone of the primary tumor can drive aggressive tumor behavior and tumor spreading." (PMID 36416959, 2023). "This has highly relevant implications in the nature of FGFR2 diagnostics (sufficient tumor cell number, determination of amplification at metastasis versus primary tumor, etc.)and on the response probability of appropriate inhibitors." (PMID 36416959, 2023). "RLY 4008 is a potent and highly selective FGFR2 inhibitor which demonstrates a strong activity against primary and acquired FGFR2 resistance mutations in cellular assays, and potent antiproliferative effects on FGFR2-altered human tumor cell lines." (PMID 37893023, 2023). "FGFR2, a receptor tyrosine kinase upregulated in many tumor cell types, plays an essential role in tumor cell proliferation, differentiation and survival." (PMID 37454027, 2023). "Fgfr1 was most highly expressed and increased uniformly in relation to the tumour proximity, however Fgfr2 - 4 were expressed at low levels and were highly variable." (PMID 37564373, 2023). "If a genetic alteration, such as ERBB2/Her2/neu or FGFR2 amplification, is homogeneously distributed uniformly across the tumor and its different clones, a single tumor-cell-bearing biopsy would be sufficient to reliably document this genetic alteration." (PMID 36416959, 2023). "FGFR2 is a therapy-relevant target in tumors of the upper gastrointestinal tract (GIT), and clinical trials are currently underway to test the efficacy of FGFR2 inhibitors." (PMID 36416959, 2023). "New therapeutic pathways for the treatment of this tumor type are still being identified with new emerging potential targets such as isocitrate dehydrogenase (IDH), fibroblast growth factor receptor 2 (FGFR2), or BRAF mutation." (PMID 37374378, 2023). "The activity of the synthesized complexes has been tested for their inhibitory actions for Her2/neu and FGFR2 that can dwindle tumor metastasis and proliferation." (PMID 38139837, 2023). "Futibatinib inhibited tumor growth in 3 of 9 PDXs, with tumor stabilization in an FGFR2-amplified model and prolonged regression (> 110 days) in an FGFR2 Y375C mutant/amplified model." (PMID 37980453, 2023). "Five patients with FGFR2 fusions showed two confirmed PRs, a SD of 24–41 weeks was achieved, and a 25% tumor reduction was observed." (PMID 37681152, 2023). "Another important factor regarding the appropriate FGFR2 fusion detection method is the amount of tumour cells and thereby tumour DNA/RNA in the sample." (PMID 35871236, 2022). "If FGFR2+ CAFs are originated from BM, before arriving in tumor beds, they or their precursors should be mobilized in BM and thereafter introduced into peripheral circulation in response to ESCC stimuli." (PMID 35941662, 2022). "Before s.c. injection of tumor cells, FGFR2+ cells accounted for about 1.08 ± 0.50%, 2.50 ± 0.32% and 1.06 ± 0.58% in P1, P2, and P3, respectively." (PMID 35941662, 2022). "FGF7/FGFR2–JunB axis was shown to abrogate the modulatory effect of PR on BCa cells and promote progression of premenopausal tumours." (PMID 35726195, 2022). "Regarding the association with other clinicopathological patient characteristics, FGFR2 status was reported to be correlated with the depth of tumor invasion, higher rate of lymph node metastasis, and more advanced stage." (PMID 35167603, 2022).
tumor (continued). "Using the same animal model, we examined the impact of tumor implantation and resection on FGFR2+ cells in BM by FCM and IF." (PMID 35941662, 2022). "Given the evidence that normal fibrocytes can further differentiate into mature fibroblasts after homing into injured sites, it is natural to wonder if FGFR2+ fibrocytes can differentiate into CAFs after arriving in ESCC tumor mass." (PMID 35941662, 2022). "Highly mutated genes like BARD1, MALT1, BRCA1/BRCA2, EIF3K, PTEN, FGFR2, and MAP3K1 were also found to overlap with SVs of the tumor sample that were identified by one or more technologies in our study." (PMID 36514120, 2022). "We next analysed oncogenomic data from Foundation Medicine (FMI) derived from 249,570 targeted tumour sequencing assays for the occurrence of FGFR2 alterations." (PMID 35948633, 2022). "Trial with hopeful results followed by ongoing FIDES-01 trial with tumours harbouring FGFR2 alterations." (PMID 36497187, 2022). "After subcutaneous injection of primary human T-ALL cells with MSCs, tumour growth was suppressed when FGF2/FGFR2 was interrupted." (PMID 36333298, 2022). "The effect of FGFR2 pathway activation is context-dependent and can evoke oncogenic and tumor-suppressive effects." (PMID 35167603, 2022). "FGFR2 overexpression caused by gene amplification is substantially more frequent in DGC and metastatic GCs than in primary GCs, and it is associated with tumor progression and poor patient survival." (PMID 35954414, 2022). "The result found that progenitors of FGFR2+ fibrocytes (FGFR2+CD34+CD45+ cells) in BM were significantly increased in KYSE30 tumor-bearing mice when compared with non-tumor-bearing mice (P < 0.01)." (PMID 35941662, 2022). "To further investigate the connection between distinct FGFR2 alterations and the FGFRi response in human tumour models, we analysed human cancer cell line pharmacogenomic datasets." (PMID 35948633, 2022). "We evaluated driver-gene enrichments among the three FGFR2 alteration categories in a tumour-type-specific manner." (PMID 35948633, 2022). "Using a break‐apart probe FISH, we detected two additional tumours with an FGFR2 rearrangement, supported by the copy number profile analysis." (PMID 35836307, 2022). "Sleeping Beauty (SB) transposon-based insertional mutagenesis screening has revealed potential tumour drivers in mice through transcriptional activation and/or truncation of target genes, and identified Fgfr2 as a top candidate driver in mammary tumorigenesis." (PMID 35948633, 2022). "In accordance with this, we demonstrate that both FGFR2 and FGF7 mRNA and protein are elevated in FP‐RMS cell lines compared to FN‐RMS cell lines and that FGF7 and FGFR2 mRNA as well as FGFR2 protein are elevated in FP‐RMS tumor samples." (PMID 34850536, 2022). "In 50 cases with strong immunostaining (FGFR2-3+), only a few cells (≤1%) of the tumor were stained." (PMID 35167603, 2022). "This in turn induces resistance to trastuzumab and lapatinib, a reaction related to the mechanism by which FGFR2 inhibitors suppress tumor progression in trastuzumab-resistant and lapatinib-resistant cells and restore sensitivity to HER2-targeted therapies." (PMID 36276152, 2022). "Collectively, these data show that the expression (combination of intensity of immunostaining and amount of immunopositive tumor areas) of FGFR2 is heterogeneous in GC." (PMID 35167603, 2022). "FGFR2 gene fusions, such as FGFR2–BICCI, FGFR2–AHCYL1, FGFR2–TACC3, and FGFR2–KIAA1598, are closely associated with tumor progression in iCCA." (PMID 35743860, 2022). "Assessment of the tumor biological function of FGFR2 necessitates consideration of the tumor phenotype." (PMID 35167603, 2022).
tumor (continued). "The biological significance of FGFR2 is a function of tumor type according to Lauren and predicts poor patient outcome in diffuse-type GC in White patients." (PMID 35167603, 2022). "FGFR2–positive diffuse-type GCs classify a small subset of patients with a poor tumor specific survival (5.29±1.3 vs. 14.67±1.9 months; p = 0.004)." (PMID 35167603, 2022). "This seems to reflect not only interactions of FGFR2‐triggered signalling separately with ER or PR, but also an impact of FGFR2 on the ER‐PR crosstalk, hence the dependence of the functional outcome of its activity on the hormonal milieu of the tumour." (PMID 35726195, 2022). "This analysis predicted that tumor-specific FAP+ fibroblasts likely originated from FGFR2+ fibroblasts or ICAM1+ telocytes." (PMID 35365629, 2022). "Archived tumor tissue samples from patients with histologically-confirmed GC or CRC suitable for chemotherapy were analyzed for FGFR2 and HER2 expression using immunohistochemistry and fluorescence in situ hybridization (HER2 in CRC only)." (PMID 35585358, 2022). "FGFR2+ fibrocytes were isolated from either ESCC patients or KYSE30 tumor-bearing mice (cell purity > 94%), transfected with lentiviral vector carrying Luciferase gene and injected into the tail vein of KYSE30 (labeled with GFP) tumor-bearing mice." (PMID 35941662, 2022). "After tumor implantation, we found that all of the mice showed a slightly increase in P1 and P3-gated FGFR2+ cells during the first week, which was followed by a rapid decrease and then stayed constant at basal level over the next 3 weeks." (PMID 35941662, 2022). "With the recent advancement in therapeutically targeting of FGFR2 fusions in iCCA, standardised molecular profiling of these tumours will be necessary." (PMID 35871236, 2022). "Lastly, we surveyed the incidence of cancer patients with concurrent FGFR2 amplification and FGFR2 fusion in their tumor specimen." (PMID 35342406, 2022). "As expected, P2-gated FGFR2+ cells were gradually decreased to basal level after active tumor removal, demonstrating that FGFR2+ cells in P2 were specifically mobilized by active tumors." (PMID 35941662, 2022). "Most studies have demonstrated FGFR2 overexpression as a prognostic marker for poor overall survival (OS) or tumor-specific survival (TSS)." (PMID 35167603, 2022). "GC patients with higher expression of Lnc_ASNR promoted tumor growth by regulating the miR-519e-5p/FGFR2 pathway." (PMID 34307360, 2021). "Downregulation or inhibition of FGFR2 can reduce tumour cell survival and migration, as well as tumour development in vivo." (PMID 33918004, 2021). "The elevated expression of FGFR2 was correlated with lymph node metastasis and TNM stage, indicating its association with tumor invasion and metastasis." (PMID 34299042, 2021). "Among the 28 patients with an FGFR2-positive tumor, the survival rate of the patients who were positive for FGFR3IIIc (n = 4) was significantly poorer than that of FGFR2IIIc-negative patients (n = 24) (p = 0.003, log-rank)." (PMID 33633310, 2021). "IHC validation on tumor samples showed an activation of the FGFR2 downstream targets AKT, p44/p42 MAPK, p38 MAPK, STAT1, and STAT3." (PMID 34480077, 2021). "In conclusion, our study provided the first comprehensive pancancer view of FGFR2 abnormal expression, methylation, alteration, and their therapeutic and prognostic implications, covering 10,967 tumor samples across 32 cancer types." (PMID 33968743, 2021). "It has been suggested that such a correlation is due to the presence of a population of tumor-initiating cells, which express high levels of FGFR2 together with GABRA4 and FOXA1." (PMID 33535617, 2021).